AVPI1 (arginine vasopressin induced 1)
Description:
May be involved in MAP kinase activation, epithelial sodium channel (ENaC) down-regulation and cell cycling.
Synonyms: PP5395; VIP32; VIT32
Tractability: Antibody: the Human Protein Atlas places it where antibodies can reach.
Gene: Protein-coding gene on chromosome 10 (97,677,422 to 97,687,561, reverse strand). Ensembl gene ENSG00000119986.
Subcellular location (Human Protein Atlas): Nucleoplasm; Plasma membrane
Gene Ontology:
Molecular function: protein binding
Biological process: positive regulation of MAPK cascade
Genetic constraint (gnomAD): Loss-of-function variants: 9 observed, 13.41 expected, observed/expected ratio (o/e) 0.67, 90% interval 0.4 to 1.17. The upper end of that interval is the gene's LOEUF score, 1.17, which puts it in group 5 of 6, group 1 being the genes least tolerant of losing a copy. Missense variants: 207 observed, 197.71 expected, observed/expected ratio (o/e) 1.05, 90% interval 0.93 to 1.17. Synonymous variants: 68 observed, 79.44 expected, observed/expected ratio (o/e) 0.86, 90% interval 0.7 to 1.05.
Homologues: Orthologues: chimpanzee AVPI1 (97% identical), macaque AVPI1 (95% identical), pig AVPI1 (91% identical), dog AVPI1 (88% identical), rabbit AVPI1 (86% identical), guinea pig AVPI1 (79% identical), rat Avpi1 (75% identical), mouse Avpi1 (73% identical), tropical clawed frog AVPI1 (48% identical), zebrafish avpi1 (31% identical).
Diseases named in the same sentence as AVPI1 in open-access papers:
AVPI1 is named in the same sentence as 8 diseases in open-access papers, as found by Europe PMC text mining. Sharing a sentence is not in itself a finding about the gene and the disease. The quoted sentences say what the papers report.
melanoma (2 papers, 2024 to 2025). A malignant, usually aggressive tumor composed of atypical, neoplastic melanocytes. "Although existing research has associated AVPI1 with the development and progression of cancers like melanoma and prostate cancer, its role in colorectal cancer and resistance to chemotherapy agents such as 5-FU and oxaliplatin has not yet been investigated." (PMID 39886381, 2025). "AVPI1 has also been reported to be correlated with the invasiveness of melanoma cells." (PMID 38365771, 2024).
alcohol dependence (1 paper, 2024). Physical and psychological dependence on alcohol. "Moreover, FAM124B is related to anorexia nervosa, and AVPI1 is associated with alcohol dependence." (PMID 39020437, 2024).
colorectal cancer (1 paper, 2025). A primary or metastatic malignant neoplasm that affects the colon or rectum. "On the other hand, a recent study on colorectal cancer cell lines showed that AVPI1 expression was significantly increased after cisplatin treatment." (PMID 39886381, 2025).
cancer (2 papers, 2023 to 2025). A tumor composed of atypical neoplastic, often pleomorphic cells that invade other tissues. "Interestingly, AVPI1, FKBP8, and ALDH2, which were most negatively correlated with NUP205 in LGG, were all reported to be tumor suppressor genes in cancer." (PMID 37284202, 2023).
AVPI1 also shares sentences with these, for which no sentence is quoted: anorexia nervosa (1 paper); Obesity (1); prostate carcinoma (1); tumor (1).